AMH (anti-Mullerian hormone)
Diseases named in the same sentence as AMH in open-access papers (continued):
Sharing a sentence is not in itself a finding about the gene and the disease.
Infertility (continued). "Several AMH–age nomograms have been reported before; however, most of the studies used hospital inpatient samples, particularly samples from infertile women instead of healthy females." (PMID 39446778, 2024). "The rate of decline OF AMH was found to be 0.192 (± 0.05) in fertile group and 0.172(± 0.04) in the infertile group." (PMID 39446778, 2024). "AUC values of single independent predictors (female age, infertility type, duration of infertility, surgical procedures, ovulation monitoring and AMH) were significantly lower than that of the predictive nomogram." (PMID 39015183, 2024). "The three groups of patients showed significant statistical differences (p < 0.05) in BMI, history of pregnancy, infertility type, AMH, basal LH and AFC." (PMID 39072274, 2024). "The age cut-off for decline in AMH (< 1.2 ngm/ml)was 31.2 and 33.2 years among the fertile and infertile women respectively, while it was 34.4 and 31.7 years among fertile and infertile women respectively for AFC (< 5)." (PMID 39446778, 2024). "Confounding factors including age, BMI, duration of infertility, previous IVF attempts, types of infertility, AMH levels, endometrial thickness, day of ET, and the proportion of transferred embryos were considered in this analysis." (PMID 38997744, 2024). "The following twelve factors were subjected to univariate analysis: patient age, duration of infertility, cause of infertility, type of protocol used, induction length in days, type of medication, AFC, FSH, TSH, level of estradiol, level of prolactin, and AMH." (PMID 38714986, 2024). "The postoperative AMH concentrations were 1.04 (IQR 0.89) ng/ml for patients with infertility and 0.31 (IQR 3.14) ng/ml for patients who became pregnant postoperatively, while the difference was not significant (p=0.885)." (PMID 38562412, 2024). "tSB (P = 0.005), tB (P < 0.001), tSB-t8 (P = 0.05), tB-tSB (P < 0.001), infertility duration (P < 0.001), and level of AMH (P = 0.047) were significantly different between euploid and aneuploid embryos." (PMID 39010092, 2024). "Now, we show a link between serum AMH and gonadal function in infertile men with impaired semen quality and compare the effect of high-dose vitamin D supplementation versus placebo on serum AMH." (PMID 36855109, 2023). "The result suggested age, duration of infertility, type of infertility, FSH, LH, AMH, and AFC were all associated with HOR (all P< 0.05)." (PMID 38047110, 2023). "The duration of infertility and anti-Mullerian hormone (AMH) levels were also found to influence implantation rate, clinical pregnancy rate, and live birth rate (all P < 0.05)." (PMID 37842291, 2023). "The authors concluded that the lower AMH levels suggest a diminished ovarian reserve and recommended considering assisted reproductive techniques for infertile wwCF." (PMID 37501150, 2023). "The average age, BMI, infertility duration, AMH, bFSH, endometrial thickness, number of embryos transferred, high-quality embryo rate and infertility factors were not significantly different in patients in each group." (PMID 37990167, 2023). "Baseline characteristics, such as age, body mass index (BMI), years of infertility, AMH level, were comparable between the two treatment groups." (PMID 37550681, 2023). "In contrast, AMH, age, T, type of infertility, duration of infertility, methods of ART, protocol, type of transfer embryos, and number of embryos transferred showed no statistical significance (P > 0.05)." (PMID 37554761, 2023). "Even then, AMH is a must biomarker test for therapeutic intervention among women seeking help in infertility clinics to evaluate ovarian reserve for over 30 years." (PMID 38077683, 2023). "This cross-sectional type of observational study included 101 healthy infertile women aged 20-35 years and with low serum AMH." (PMID 38077683, 2023).
Infertility (continued). "The groupswere comparable with respect to age, factor of infertility and baseline AMH.The antagonist protocol was significantly more prescribed to the high P4group (p<0.001)." (PMID 35916460, 2023). "Several other studies have measured serum AMH in both fertile and infertile men but most of these cohorts are relatively small." (PMID 36855109, 2023). "The factors affecting implantation, clinical pregnancy, and live birth rates were duration of infertility, AMH levels, and AFC (P < 0.05)." (PMID 37842291, 2023). "In women with PCOS, elevated anti-mullerian hormone (AMH) levels play an important role in disrupting long-term ovarian physiology with high concentrations being consistent with an increased rate of infertility." (PMID 37239774, 2023). "This study also revealed that 55.7% of the infertile females below 35 years of age had low AMH; among these cases, 50.7% had low AFC correspondingly." (PMID 38077683, 2023). "Basic characteristics such as age, body mass index, duration of infertility and anti-mullerian hormone (AMH) levels were similar in both groups." (PMID 37250564, 2023). "In this study, we evaluated the relationship between serum AMH values and the clinical pregnancy (CP) rates of female partners with unexplained infertility undergoing intrauterine insemination utilizing varying ovarian simulation protocols." (PMID 38022255, 2023). "Association between unsuccessfully and successfully conceived women age and duration of infertility, number of retrieved oocytes, number of fertilized oocytes and AMH hormone." (PMID 37576599, 2023). "The median AMH values were 4.23 ng/mL, 3.48 ng/mL, 2.43 ng/mL, 1.28 ng/mL, and 0.52 ng/mL among Indian infertile females of age group in 20-25, 26-30, 31-35, 36-40 and 40-44 years, respectively." (PMID 38077683, 2023). "In conclusion, our study shows a correlation between TSH and AMH values in a population of infertile women." (PMID 37925426, 2023). "One woman, aged 24, had an AMH of 0.85, a value below the 2.5th percentile for her age; indeed, she is currently undergoing fertility treatments and has experienced 4 years of infertility since trying to conceive." (PMID 37501150, 2023). "The POSEIDON criteria divide infertile patients into four groups according to age, anti-mullerian hormone (AMH), and antral follicle count (AFC): Group 1: patients aged below 35 years with a good ovarian reserve (AFC ≥ 5, AMH ≥ 1.2 ng/mL) but unexpected POR." (PMID 36798666, 2023). "We observed heterogeneity among the groups: the women who used the dual trigger were older and with a longer time of infertility, and the group that used agonist GnRH had a better ovarian reserve (higher AMH and AFC values and lower values of base FSH)." (PMID 35108732, 2022). "in 1935 infertile women of which only 9.6% were diagnosed with PCOS, showed a strong positive association between serum testosterone and AMH levels." (PMID 35757414, 2022). "This is a case of secondary infertility with cavity adhesions with low AMH and low antral follicular count." (PMID 36081974, 2022). "This conclusion is confirmed by recent data indicating that serum AMH level in infertile patients with OMA is significantly lower than in the control group and patients with bilateral OMAs have lower AMH levels than those with unilateral OMA." (PMID 34405378, 2022). "AMH is best validated as a predictor of response to controlled ovarian hyperstimulation in patients with infertility." (PMID 35566443, 2022). "Targeted knockout of the AMH gene caused early exhaustion of mice primordial follicle pools, leading to POI and infertility." (PMID 35462905, 2022). "The factors with a P-value < 0.2 were as follows: age, AFC, AMH, infertility duration, overall ART attempts, progesterone level on HCG day, and GVBD rate." (PMID 36699025, 2022). "In our healthcare system, serum assays for anti‐Müllerian hormone (AMH) are readily accessible for all those receiving health care for AUB or infertility." (PMID 35983674, 2022).
Infertility (continued). "The confounding factors they considered included parental ages, BMI, AMH levels, duration of infertility, endometrial thickness five days before transfer, number of previous gestations and transfers, and days of ET." (PMID 35250858, 2022). "The patients who were confirmed as clinical pregnancy have more antral follicle count (AFC, P=0.034), higher basal anti-müllerian hormone (AMH, P=0.049) level, shorter infertility duration (P=0.036), and fewer overall ART attempts (P=0.004)." (PMID 36699025, 2022). "Our two groups were comparable for patient age, smoking status, ovarian reserve represented by AMH, infertility indication and the rank of attempt of IVF +/- ICSI except for body mass index." (PMID 36619564, 2022). "It was found that AMH was correlated with age, infertility duration, BMI, FSH, FSH/LH, and P. Furthermore, AFC was correlated with age, FSH, and FSH/LH." (PMID 36539903, 2022). "The results of curve fitting revealed a curvilinear relationship between FORT and cumulative IVF outcomes, after adjustment for age, BMI, years of infertility, AMH, treatment plan and type of PCOS." (PMID 36601009, 2022). "The multivariate logistic regression analysis adjusted for the following confounders: age, BMI, years of infertility, AMH, treatment plan, type of PCOS." (PMID 36601009, 2022). "Spearman correlation analysis revealed that serum AMH levels were correlated with age, duration of infertility, BMI, FSH, FSH/LH, and P, and AFC was correlated with age, FSH, and FSH/LH." (PMID 36539903, 2022). "Here, we found that the expression level of miR-484 in GCs from the follicular fluid of infertile women was negatively correlated with serum levels of AMH and AFC." (PMID 35173533, 2022). "In general, infertility in men is a heterogeneous disease but by identifying serum levels of AMH as a positive predictive biomarker, it seems we can select the group of infertile men where treatment with denosumab most likely will increase their semen quality." (PMID 35733213, 2022). "Serum AMH levels are a marker of ovarian reserve that are commonly measured in patients seeking infertility treatment." (PMID 33828986, 2021). "After adjusting for age, infertility duration, past live‐births, and AMH, the adjusted odds for CLBR in UI1 was 0.48 (95%CI = 0.28‐0.82; P = .007)." (PMID 33850452, 2021). "Serum anti-Mullerian hormone (AMH) is a widely used marker of functional ovarian reserve in the assessment and treatment of infertility." (PMID 34108942, 2021). "Univariate logistic regression analysis revealed that the female age, years of infertility, BMI, basal LH, AMH, AFC, treatment cycles, Gn dosage, duration of Gn administration, number transferable embryos significantly influenced the prospect of live birth." (PMID 34273144, 2021). "Elevated AMH and LH levels as well as hyperandrogenism are frequently present in infertile women with PCOS, a common endocrine disease often diagnosed by reproductive specialists." (PMID 33828986, 2021). "Three hundred fourteen women with infertility due to various etiologies were enrolled in this study (172 individuals with Anti-Mullerian hormone (AMH) level ≥ 1.1 ng/ml and 142 individuals with AMH < 1.1 ng/ml)." (PMID 34598733, 2021). "We have calculated an AMH threshold specifically fora normal-ovulatory subgroup of infertile women withPCOM." (PMID 33687164, 2021). "Given that around 10–30% of patients presenting to doctors with infertility were diagnosed as decreased ovarian reserve based on an AMH level around 1.0 ng/ml or 10th centile, this study also chose the age-specific 10th centile as the cut-off value of low AMH." (PMID 33673814, 2021). "Both basic FSH and AMH are good indicators for predicting ovarian responsiveness in infertile patients." (PMID 34059771, 2021). "In our cohort, approximately one in ten infertile women had a discrepancy in the measured AMH concentration and AFC." (PMID 34454544, 2021).
Infertility (continued). "Female age, infertility duration, AMH, and BMI were all balanced between the two groups after matching." (PMID 34925238, 2021). "The women undergoing infertility treatment were classified according to the ovarian reserve into three groups; normal (n = 80), high (n = 40), and low (n = 39) based on AMH level as described by Antonio La Marca and Sunkara1." (PMID 34172798, 2021). "Roy15 showed a marked (>10‐fold) elevation of ovarian AMH mRNA in FSHβ−/− infertile mice compared to wild‐type or FSHβ−/−/hFSHβWT controls, supporting the inhibitory role of FSH on AMH expression in this system." (PMID 33855196, 2021). "This cross-sectional study investigated the prevalence of infertility and AMH level among women of childbearing age in Henan Province, China, for the first time." (PMID 34930324, 2021). "It would be valuable to considerthe AMH cut-off values for different BMI categories inorder to develop an individually tailored, effective, and safestimulation programme for infertile women with PCOM." (PMID 33687164, 2021). "Age, BMI, infertility diagnosis, duration of infertility, AMH, day 3 FSH, basal E2, and glucose were considered potential confounders and were adjusted for in subsequent analyses." (PMID 33763032, 2021). "With the development of serum AMH immunoassays it has become apparent that AMH is a clinically useful marker of functional ovarian reserve and thus of clinical value in the treatment of infertility, where measuring the follicle reserve is important." (PMID 34108942, 2021). "The mean ± SD of AMH for the fertile group was 3.734 ± 0.151 ng/ml and 3.557 ± 0.262 ng/ml for the infertile group." (PMID 34930324, 2021). "A total of 296 infertile patients with AMH measured (younger group, aged 25-38 years; older group, aged 39-42 years) were included in this study." (PMID 34105924, 2021). "Most of the available data on AMH levels have been focused on women with infertility and/or polycystic ovary syndrome (PCOS)." (PMID 34300357, 2021). "Very recently, a reduction in miR-21-5p abundance level was observed in the plasma of infertile women with abnormal AMH levels." (PMID 34172798, 2021). "After adjusting for potential confounders, serum DHEA-S levels positively correlated with serum AMH levels in infertile women (β = 0.103, p < 0.001)." (PMID 33803980, 2021). "The difference persists despite adjustments for age, previous live births, AMH, and infertility duration." (PMID 33850452, 2021). "In the present study, it appears that women treated with rFSH had AMH values corresponding to “infertility” (81.8%) while the rest had AMH values corresponding to “fertility” (18.2%)." (PMID 33628769, 2021). "We report the management of a patient with AGCT characterized by infertility, abnormally elevated AMH levels, and hyperandrogenism." (PMID 33828986, 2021). "This study demonstrated that higher serum DHEA-S levels correlated with higher serum AMH levels in infertile women after adjusting for potential confounding factors." (PMID 33803980, 2021). "The objective of this study was to investigate serum levels of anti-Müllerian hormone (AMH) innormal-ovulatory infertile women with polycystic ovarian morphology (PCOM) and their association with ovarianhyper-response." (PMID 33687164, 2021). "Before PSM, the duration of infertility and AMH were substantially different (|SD| >0.1) between the two groups." (PMID 34925238, 2021). "The analysis makes adjustments for female age, infertility duration, past live‐births, past treatments, and AMH." (PMID 33850452, 2021). "On the other hand, the majority of women who received hMG also had AMH values corresponding to infertility (38.1%), while 33.3% were women with AMH values corresponding to menopause and 28.6% were women with AMH values corresponding to fertility." (PMID 33628769, 2021). "Another prospective study indicated that the mean serum level of AMH in infertile women aged 24 to 48 years on day 3 of the menstrual cycle was 2.84 ± 1.57 ng/mL." (PMID 33907092, 2021).
Infertility (continued). "The serum AMH levels significantly increased across increasing DHEA-S quartile categories in infertile women (p = 0.014) using generalized linear models after adjustment for potential confounders." (PMID 33803980, 2021). "The adjusted odds ratio for live‐births adjusting for confounding variables age, infertility duration, past live‐births, past treatments, and AMH was 0.48 (95% CI = 0.28‐0.82; P = .004)." (PMID 33850452, 2021). "From the serum AMH values of women, it appears that for rFSH treatment (N = 11), most women had AMH values corresponding to infertility (81.8%) while the rest had AMH values corresponding to fertility (18.2%)." (PMID 33628769, 2021). "Years of infertility (3.32 ± 2.60 vs. 3.90 ± 2.85; P = 0.003) and AMH level (4.31 ± 2.01 vs. 4.73 ± 2.95; P = 0.028) were lower in the RIF group than in the control group." (PMID 35211088, 2021). "Women that present with infertility due to DOR or women who undergo treatments with high [AMH], if managed appropriately, can produce more usable blastocysts per IVF treatment, thus increasing the potential for a successful pregnancy." (PMID 33044971, 2020). "Attributes like age, AMH, BMI, duration of infertility, previous live birth, previous miscarriage, etc. and type of infertility (tubal, male factor, anovulatory, unexplained, and others) are considered." (PMID 33262383, 2020). "Clinical studies demonstrated that decreased AMH levels indicates reduced ovarian responsiveness to exogenous gonadotropin administration, and poor pregnancy outcome in women undergoing infertility treatment." (PMID 32586307, 2020). "The mean age of patients was younger and the mean AMH level was higher, compared to previous studies including patients diagnosed with infertility and performing ovarian stimulation for IVF procedures." (PMID 33085706, 2020). "In view of its utility in evaluating fertility (ovarian reserve), assessment of age-specific variation in AMH levels is central for infertility workup, as serum AMH reflects AMH production only from functioning follicles." (PMID 32586307, 2020). "Although the ability of AMH to predict reproductive potential is controversial, it is an excellent predictor of oocyte yield among women with infertility undergoing controlled ovarian hyperstimulation for in vitro fertilization (IVF)." (PMID 32487204, 2020). "Anti-Müllerian hormone (AMH) as a marker of ovarian reserve is an essential aspect of infertility testing." (PMID 33633682, 2020). "Clinically, AMH determination is utilized in assessing ovarian reserve in infertility diagnosis, premature ovarian failure, and polycystic ovary syndrome (PCOS)." (PMID 32586307, 2020). "On comparison, the vitamin D levels were lower in fertile than infertile females, which was significant (p = 0.04), and AMH levels were lower in cases than the control group." (PMID 32481491, 2020). "There were no significant group differences in age, body mass index, duration of infertility, basal antral follicle count, and serum AMH concentrations (p>0.05 for all)." (PMID 33343970, 2020). "While markers of ovarian reserve such as AMH are routinely used to predict outcomes of IVF cycles in a general infertility population, the value of AMH as an overall predictor of reproductive potential is unclear." (PMID 30923623, 2019). "The groups weresimilar with respect to age, body mass index (BMI), duration of infertility, antralfollicle count, AMH levels and basal FSH and estradiol." (PMID 30614665, 2019). "In various studies the reasons such as reduced ovarian reserve (which is caused by low levels of AMH and higher level of FSH) and a reduction in oocyte and embryo quality discussed as factors contributing to infertility in patients with endometriosis." (PMID 30775688, 2018). "AMH levels are now routinely used in the diagnosis and treatment of infertility, particularly to assess for ovarian reserve or in the evaluation of polycystic ovarian disease (PCOS)." (PMID 30094759, 2018).